CD44 (CD44 molecule (IN blood group))
Diseases named in the same sentence as CD44 in open-access papers (continued):
Sharing a sentence is not in itself a finding about the gene and the disease.
colorectal cancer (continued). "Nevertheless, whether miR-6511b-5p is involved in metastasis by regulating CD44 in pMMR colorectal cancer has not been explored." (PMID 35590122, 2022). "Compared with CD44 negative human colorectal cancer cells (COLO 201), CD44 positive cells showed stemness characteristics and displayed lower sensitivity to the anti-tumor drug 5-FU, accompanied by the up-regulation of tumor stemness and chemoresistance-associated genes." (PMID 33303029, 2020). "In addition, we also assessed expression of cancer stem cell markers, and found no significant changes in CD44, a commonly used marker for colorectal cancer stem cells." (PMID 28413604, 2017). "To verify that NRIP2 is expressed at a higher level in CCICs, we isolated CD44+CD24+ colorectal cancer-initiating cells from primary colorectal P1 and SW620 cells by fluorescence-activated cell sorting (FACS) and colospheres from colorectal cancer cell lines and primary colorectal cancer tissues." (PMID 28137278, 2017). "Notably, both CD44 and CD133 have been reported as markers of CSCs in human colorectal cancer." (PMID 26418878, 2015). "However, another study has shown that only a knockdown of CD44, but not CD133, strongly prevented clonal formation and inhibited tumorigenicity in the mice xenograft model, and that CD44+ is not colocalized with CD133+ cells within colorectal cancer." (PMID 24921652, 2014). "We compared the CD44 alternative splice pattern (ASP) of three genetically different human colorectal cancer cell lines (HT25, HT29, HCT116) using a series of PCR reactions and next- generation sequencing method, as well as identified a colorectal adenocarcinoma specific CD44 ASP." (PMID 23151220, 2012). "Although both CD44 and CD133 were reported as putative markers for many cancer-specific CSCs, including colorectal cancer (described in Introduction), it remains to be resolved whether they are of equal functional importance and what are their interrelationships." (PMID 20630067, 2010). "Authors reported that CD44+ did not colocalize with CD133+ cells within colorectal cancer." (PMID 20630067, 2010). "Additionally, studies indicated that E. faecalis in the gut induces colitis and upregulates TGF-β expression in intestinal epithelial cells, triggering the transformation of CD44-noncancerous stem cells into CD44+ cancer stem cells, intensifying colorectal cancer development." (PMID 40520902, 2025). "SIX is enriched in the CD44+CD24-/low subpopulation, whereas DACH might act as a tumor suppressor to reduce the number of BCSC subpopulations in vitro and in vivo though phosphorylating GSK3β and inhibiting Wnt signaling, compliance with findings in colorectal carcinomas." (PMID 27793013, 2017). "Furthermore, we analyzed the stemness scores of these CSC gene-expressing niches and found that CD44-positive niches exhibited the highest stemness across all ST niches, suggesting that CD44-positive niches may represent the CSC niches in our colorectal cancer tissues." (PMID 40069574, 2025). "BRG1 influences the methylation of CD44 promoters in several cancer cell lines, such as SW13, C33A, HeLa, and Saos-2, but this phenomenon has not been detected in colorectal cancer cell lines." (PMID 35590122, 2022). "A 48h-treatment with 50 μM of curcumin induced apoptosis in CD44+ cells but not in CD44− cancer cells, suggesting that curcumin preferentially targets the CSC subpopulation within colorectal cancer cells." (PMID 34201298, 2021). "Among human colorectal cancer (COLO 201) cells, CD44 positive cells displayed remarkably enhanced capacity of tumor formation in compared with CD44 negative counterparts in immunodeficient mice." (PMID 33303029, 2020).
colorectal cancer (continued). "The data are supported by a previous study involving 60 patients, in which it was shown that CD44 and CD133 positive cells did not co-localize within colorectal cancer." (PMID 22895640, 2012). "Collectively, these findings define the functional cascade”LOX1– macropinocytosis–GHSACA internalization” and confirm that GHSACA is internalized into colorectal cancer cells predominantly via the LOX1-mediated macropinocytosis pathway, with CD44 playing no discernible role in this process." (PMID 41488675, 2025). "While acknowledging that this may not reflect colorectal cancer TME dynamics, EO771 was selected for its immunocompetent, macrophage-rich environment and high CD44 expression, avoiding the limitations of immunocompromised xenograft models." (PMID 40160820, 2025). "Consistent with this, our comparative study between radioresistant and radiosensitive colorectal cancer cells showed that CD44 expression, but not that of CD133, was selectively increased in radioresistant colorectal cancer along with acquiring the properties of colorectal CSCs after irradiation." (PMID 33445526, 2021). "However, CD44+/CD24+ cells, not CD44+/CD24− cells, harbor CSC capacity in pancreatic and colorectal cancers." (PMID 27521216, 2016).
prostate carcinoma (377 papers, 2002 to 2025). A carcinoma that arises from epithelial cells of the prostate gland. "Prostate cancer cells can disseminate to other parts of the body through bone marrow endothelial cells, which have increased levels of membrane-associated CD44." (PMID 38496894, 2024). "Studies have shown that increased CD44 expression is associated with advanced prostate cancer stages, higher Gleason scores and poorer prognosis." (PMID 39441869, 2024). "The interaction of these hormones (androgens) with their receptors, including CD44, is considered the hallmark event for the initiation and establishment of prostate cancer." (PMID 37108498, 2023). "In consistent with these clinical reports, PC-3 cells, which are derived from metastatic bone of prostate carcinoma and positive for stem cell-associated marker CD44, expressed high levels of JICD." (PMID 36428807, 2022). "Here, we analyzed the expression patterns of two PCSC-associated membrane markers, CD44 and EpCAM, in 3D-cultured prostatospheroids derived from three different prostate cancer cell lines (AR-positive LNCaP and VCaP; AR-negative DU145)." (PMID 32183880, 2020). "Gupta and coworkers demonstrated that Integrin αvβ3 and CD44 are involved in prostate cancer patients bone loss by promoting osteoclastogenesis through the RUNX2/Smad 5/receptor activator of NF-κB ligand pathways." (PMID 32204402, 2020). "Pilot studies were carried out to explore the expression of the CD44 variants v3-v10 on prostate cancer cells." (PMID 33218199, 2020). "Osteopontin has also been shown to increase both standard and variant CD44 expression in prostate cancer." (PMID 33062960, 2020). "In conclusion, CD44 expression is significantly associated with tumor aggressiveness in prostate cancer and activation of IL-6 signaling leads to a suitable microenvironment for the induction of CD44 expression." (PMID 31315262, 2019). "The expression of CD44 in prostate cancer is significantly associated with tumor aggressiveness, and IL-6 signaling leads to a suitable microenvironment for the induction of CD44 expression." (PMID 31315262, 2019). "Silibinin inhibited CD44 promoter activity, caused a 90% inhibition of total CD44, and decreased the levels of CD44v7-10 RNA and protein in prostate cancer cells." (PMID 29747682, 2018). "Hypermethylation of the 5′ CpG island of the CD44 gene was observed in 31 of 40 primary prostate cancer specimens and was associated with CD44 transcriptional inactivation." (PMID 29747682, 2018). "Stated these confusing results on CD44 variants expression in human PCa samples, we analyzed the expression pattern of CD44v8-10 in 30 normal prostate and in prostate cancer tissues from 60 patients using immunohistochemistry." (PMID 30112117, 2018). "High CD44 expression is a characteristic of cancer stem cells functionally linked to prostate cancer metastasis." (PMID 29108245, 2017). "CD44 is known to play a similar role in prostate cancer, as it mediates the adhesion between prostate cancer cells and endothelial cells and it is also implicated in prostate cancer cell invasion." (PMID 28886116, 2017). "Since the cell adhesion molecule CD44 has been linked in different cancer stem cells such as breast, liver, ovarian, pancreatic and prostate cancers, we next evaluated CD44 expression status by flow cytometry." (PMID 27248169, 2016). "Another study indicates that RBM3 attenuates the stemness and tumorigenesis of prostate cancer cells by inhibiting CD44 variant splicing, although this finding is in contrast to findings in colorectal cancer." (PMID 27147467, 2016). "Many malignant tumors, such as head and neck, breast, and prostate cancer, express high levels of CD44 or its variants." (PMID 26821610, 2016). "Systematic studies from our lab have demonstrated that CD44 is a prostate cancer stem cell (PCSC) enrichment marker that plays a causal role in prostate cancer (PCa) development and metastasis." (PMID 27447749, 2016).
prostate carcinoma (continued). "Catenins, as well as CD44, are associated with E-cadherin in regulating prostate cancer cell adhesion." (PMID 25967040, 2015). "Epithelial–mesenchymal transition (EMT) has been linked to cancer stem-like (CD44+) cell in the prostate cancer (PCa) metastasis." (PMID 25483103, 2015). "A considerable number of studies indicate that CD44 variant isoforms correlate with bad prognosis in patients with most human cancers except in neuroblastomas and prostate cancer." (PMID 25999946, 2015). "In PC3 prostate cancer cells, which express relatively high levels of both CD44 and TrkA, NGF stimulation resulted in the association of TrkA with CD44 at the plasma membrane, as demonstrated using the PLA signal of TrkA/CD44." (PMID 25840418, 2015). "In prostate cancer an increased number of holoclones is associated with the expression of the putative stem cell markers CD44, integrin α2β1, CD133, PSAlo expression and aldehyde dehydrogenase 1 (ALDH) activity." (PMID 24587067, 2014). "This is consistent with prostate cancer, in which CD44s is a tumor suppressor but certain CD44 variants are oncogenes and promote growth." (PMID 24491153, 2014). "Expression of CD44 (standard or variant isoforms) has been considered a prognostic marker for the progression of prostate cancer." (PMID 22966907, 2012). "The present study was undertaken to determine the possible mechanisms involved in the formation of osteolytic lesions associated with metastasis of prostate cancer cells to bone and the significance of CD44 and αvβ3 signaling." (PMID 22966907, 2012). "Our recent studies have shown an increase in the surface expression of CD44 isoforms (sCD44 and v4-v10 variant CD44) in prostate cancer cells over-expressing osteopontin (PC3/OPN)." (PMID 20868520, 2010). "Prostate cancer cell lines sorted for high expression of CD44 have been associated with enhanced expression of "stemness" markers including BMI, β-catenin, SMO, and Oct 3/4." (PMID 20718984, 2010). "In addition, high expression of CD44 was reported to be associated with prostate cancer cell migration and proliferation." (PMID 38783892, 2024). "Loss of CD44 has been indicated in most prostate cancer due to extensive hypermethylation of CpG." (PMID 35457063, 2022). "Previously, we showed that KIFC1 is associated with CD44 in prostate cancer and gastric cancer." (PMID 34768355, 2021). "Furthermore, in most prostate cancer cases, the loss of CD44 expression is associated with extensive hypermethylation of the CpG island CD44 promoter region." (PMID 34944493, 2021). "A search of the literature revealed that CD44 was required for SRGN to promote aggressiveness of non-small cell lung cancer 41, and that CD44-positive prostate cancer cells were significantly more susceptible to the inhibitory effect of MDK-knockdown on cell viability." (PMID 33456569, 2021). "Loss of CD44 expression is associated with poor prognosis in prostate cancer." (PMID 32434417, 2020). "Although CD44 and its spliced variants exhibit downregulation in high-grade and metastatic prostate cancer, their altered expression patterns show a correlation to prognosis in prostate cancer." (PMID 32183880, 2020). "Furthermore, CD44-expressing prostate cancer cells expressed more marked EMT changes, associated with higher invasiveness." (PMID 31315262, 2019). "The predominant CD44 splice variant in prostate cancer-bound fibronectin required HA bound to CD44." (PMID 29747682, 2018). "However, another study suggested that high RBM3 attenuated the stemness and tumorigenesis by inhibiting CD44 variant splicing in prostate cancer cells." (PMID 28118608, 2017). "Furthermore, CD44 high expression level was associated with biochemical recurrence and distant metastasis, making CD44 a marker of poor prognosis in prostate cancer." (PMID 28430640, 2017). "Therapeutic NED has also been identified as a cause of radioresistance that may be limited to CD44+ prostate cancer stem cells." (PMID 27703211, 2016).
prostate carcinoma (continued). "To address the question whether the mtDNA depletion PC3 cells were of greater cell stemness, we examined the CD44 expression in these cells since CD44 expression has been linked to prostate cancer stem cells (CSC)s." (PMID 27248169, 2016). "Conversely, the degree of malignancy of some cancers such as prostate cancer, is associated with loss of CD44, suggesting that CD44 could be a tumor suppressor." (PMID 23445749, 2013). "The initial formation of tumors from high numbers of paraclone cells may be explained by the high intrinsic tumorigenicity of PC3 cells, a high fraction of which express CD44, which has been associated with prostate cancer cell tumorigenicity." (PMID 21190562, 2010). "Moreover, CD44 silencing experiments in prostate cancer were performed to demonstrate that the loss of this receptor activity is associated with tumor recurrence and progression; also, the majority of prostate cancer metastases lack the expression of this molecule." (PMID 32349323, 2020). "However, CD44 expression is linked to favorable prognosis in prostate cancer." (PMID 32434417, 2020). "Moreover, in the late nineties several authors, by using immunohistochemical analysis of human prostate cancer specimens, described a down-regulation/loss of CD44 expression during human prostate cancer progression correlated with higher tumour grade and distant metastasis." (PMID 30112117, 2018). "Interestingly, 100% of prostatic small cell NE carcinomas, an aggressive variant of prostate cancer that is composed of highly proliferating NE cells, have CD44 expression, whereas its expression was detectable only in a minority of small cell NE carcinoma from other organs." (PMID 25927031, 2015). "Early studies revealed that at least five prostate cancer cell lines released the CD44 protein into the media by shedding it when grown in serum-free media." (PMID 41440277, 2025). "There is a downregulation of CD44 expression in metastatic stages of prostate cancer, while migration is decreased." (PMID 40190563, 2025). "Flow cytometry analysis showed that CD44+CD133+ prostate cancer stem-like cells accounted for 0.86% of the LNCaP population and 5.30% of the unsorted C4-2B population." (PMID 40735647, 2025). "CD44 is a drug target in Prostate Cancer and Neuroblastoma, its prevalence in HGSOC tumor cells underscores its potential significance as a therapeutic target." (PMID 40036264, 2025). "Similar to CSCs, prostate cancer stem cells (PCSCs) are distinguished by markers such as CD44, CD133, CD49f, Integrins α2/β1, ALDH1, KLF4, SOX2, NANOG, and P63." (PMID 39806412, 2025). "In prostate cancer, CD44+/α2β1hi/CD133+ cells undergo cell differentiation to an androgen receptor-positive phenotype similar to prostate cancer in situ." (PMID 39919692, 2025). "QC-loaded hyaluronic acid-modified nanoliposomes (LP-Quer-HA) were employed to target prostate cancer stem cells (CSCs) that overexpress CD44+ receptors." (PMID 39416904, 2024). "CD44-positive prostate cancer cells were also reported to be resistant to docetaxel after a few months of treatment due to the elevation of AKT-dependent drug transporter ABCB1 and expression of class III β-tubulin." (PMID 38542115, 2024). "The use of these nanoliposomes as a QC delivery system increased its potency at lower concentrations, effectively diminishing the CD44+ cell population and preventing the proliferation and migration of prostate cancer cells." (PMID 39416904, 2024). "Lai and his co-workers observed that resistant prostate cancer cells are characterized by the presence of CD44+ and/or CD133+ which make cells resistant to docetaxel toxicity." (PMID 39003454, 2024).